AEBP1 (AE binding protein 1)
Diseases named in the same sentence as AEBP1 in open-access papers (continued):
Sharing a sentence is not in itself a finding about the gene and the disease.
colon cancer (3 papers, 2020 to 2024). "For example, AEBP1 in colon cancer promotes cell proliferation, migration, and in vitro tube formation." (PMID 33224311, 2020). "For example, upregulation of AEBP1 in colon cancer accelerates the progression of colon cancer by promoting angiogenesis." (PMID 33224311, 2020). "In our study, we found that AEBP1 may be a predictive target for response after FOLFIRI treatment in colon cancer." (PMID 36523769, 2022). "Therefore, AEBP1, BGN, and TAGLN have been identified as potential biomarkers related to the response to FOLFIRI treatment of colon cancer." (PMID 36523769, 2022). "In addition, the gene expression levels of AEBP1, BGN, and TAGLN were negatively correlated with OS and DFS in colon cancer patients." (PMID 36523769, 2022). "AEBP1 and ZNF503 have not been previously related with PAH pathogenesis, and both were identified as common overregulated genes in colon cancer, suggesting their importance in the establishment of tumoral processes." (PMID 39791702, 2024).
gastroschisis (3 papers, 2013 to 2024). Gastroschisis is marked by viscera protruding, without a covering sac, from the fetal abdomen on the right lateral base of the umbilicus. "Therefore, the Feldkamp group screened AEBP1 variants in 40 gastroschisis cases." (PMID 39728087, 2024).
nonalcoholic steatohepatitis (3 papers, 2021 to 2024). "Several studies showed that AEBP1 expression correlates with severity of fibrosis in nonalcoholic steatohepatitis (NASH), where hepatic expression of the protein exacerbates the disease both in humans and mice." (PMID 37917183, 2023).
oral squamous cell carcinoma (3 papers, 2023 to 2025). "We recently reported that in oral squamous cell carcinoma (OSCC), adipocyte enhancer-binding protein 1 (AEBP1) is abundantly expressed in cancer-associated fibroblasts (CAFs), leading to CAF activation and inhibition of CD8 + T cell infiltration." (PMID 39521917, 2024). "In the present study, we aimed to clarify the role of stromal AEBP1/ACLP expression in oral squamous cell carcinoma (OSCC)." (PMID 37686580, 2023). "In the present study, we aimed to elucidate the function of AEBP1/ACLP and its usefulness as a therapeutic target in oral squamous cell carcinoma (OSCC)." (PMID 37686580, 2023).
ovarian carcinoma (3 papers, 2015 to 2020). A malignant neoplasm originating from the surface ovarian epithelium. "Taken together with the study conducted by Cheon and colleagues, upregulation of ECM components and NF-κB pathway due to AEBP1 overexpression could serve as a plausible module for AEBP1-mediated tumorigenesis in ovarian cancer." (PMID 32565808, 2020). "However, a follow-up experiment using the ovarian cancer cell line, OVCAR3, demonstrated that treating cells with TGFβ1 increased mRNA level of AEBP1." (PMID 32565808, 2020).
pancreatic cancer (3 papers, 2023 to 2025). "Integration of single-cell RNA-sequencing datasets from breast and pancreatic cancers revealed that AEBP1 is predominantly expressed in CAFs, where it is co-expressed with collagens and CAF marker genes." (PMID 41373631, 2025).
diabetic kidney disease (2 papers, 2021). Progressive kidney disorder caused by vascular damage to the glomerular capillaries, in patients with diabetes mellitus. "For example, a study on diabetic kidney disease (DKD) patients selected AEBP1 from a set of estimated glomerular filtration rate (eGFR)-correlated genes." (PMID 35008723, 2021).
endometriosis (2 papers, 2022 to 2023). The growth of functional endometrial tissue in anatomic sites outside the uterine body. "Through scRNA-seq, WGCNA, and LASSO methodologies, DES, GREM1, MBNL1, and AEBP1 emerged as crucial core genes linked to tissue stem cell markers in endometriosis." (PMID 38115253, 2023). "By employing scRNA-seq, WGCNA, and LASSO diagnostic model development methodologies, DES, GREM1, MBNL1, and AEBP1 were identified as pivotal core genes in endometriosis that display notable associations with tissue stem cell marker genes." (PMID 38115253, 2023). "A study focused on GSE51981, containing four stages of endometriosis and normal endometrium, pointed that the mRNA levels of AEBP1 and HOXB6 shifted in I/II, III/IV stages." (PMID 36532015, 2022). "AEBP1 and KLF2 were higher expressed, while DLX6, HOXB6, and RORB were lower expressed in endometriosis in the GSE7305 dataset." (PMID 36532015, 2022). "NEAT1 and XIST may regulate the expression of four TFs (AEBP1, HOXB6, RORB, and KLF2) through the lncRNA-miRNA-mRNA network and participate in the development of endometriosis." (PMID 36532015, 2022). "AEBP1 and HOXB6, together with IGF-1, CYP11A1, MMP-2, CC2D2A, IER3, STX18, maybe staging markers for endometriosis." (PMID 36532015, 2022). "Our results showed that HOXB1, AEBP1, and RORB were involved in endometriosis and SLE." (PMID 36532015, 2022). "AEBP1, HOXB6, KLF2, and RORB may be potential biomarkers for endometriosis." (PMID 36532015, 2022).
hepatocellular carcinoma (2 papers, 2019 to 2024). A malignant tumor that arises from hepatocytes. "In the current work, we detected AEBP1 expression in primary human hepatocytes and in the HepG2 hepatoma cell line." (PMID 31299062, 2019). "Co-treatment with KPA also decreased the expression of genes, regulating the progression of fibrosis (e.g., COL6A3, AEBP1, SPARC, TNC, LAMB1, BGN) and hepatocellular carcinoma (e.g., COL4A1, COL4A2, TUFT1, VCAN, NID1)." (PMID 39404414, 2024).
lymph node metastasis (2 papers, 2020 to 2021). "High levels of AEBP1 were associated with the presence of lymph node metastasis and TNM staging." (PMID 32565808, 2020). "The association of AEBP1 with lymph node metastasis may explain the poor OS rate and the manifestation of high TNM stages III and IV." (PMID 32565808, 2020). "Upregulation of AEBP1 was correlated with tumor size, histologic differentiation level, lymph node metastasis, and tumor staging." (PMID 32565808, 2020).
osteoarthritis (2 papers, 2024 to 2025). A noninflammatory degenerative joint disease occurring chiefly in older persons, characterized by degeneration of the articular cartilage, hypertrophy of bone at the margins and changes in the synovial membrane. "AEBP1 knockdown in mouse models of osteoarthritis revealed that loss of AEBP1 reversed degeneration association inflammation and ECM degradation." (PMID 39930483, 2025). "Higher AEBP1 levels were found in the articular cartilage of donors with osteoarthritis in comparison to normal counterparts." (PMID 39930483, 2025).
renal fibrosis (2 papers, 2024). A final common manifestation of a wide variety of chronic kidney diseases characterized by glomerulosclerosis and tubulointerstitial fibrosis. "Knockdown of AEBP1 expression again resulted in a diminished fibrotic response both in cultured renal fibroblasts and in an in vivo model of renal fibrosis, which was then linked to the modulation of the β-catenin signaling pathway." (PMID 38727290, 2024). "Further contradictory evidence on the role of AEBP1 in the fibrotic response is presented in a study focusing on renal fibrosis." (PMID 38727290, 2024).
acute lymphoblastic leukemia (1 paper, 2021). Leukemia with an acute onset, characterized by the presence of lymphoblasts in the bone marrow and the peripheral blood.
acute myeloid leukemia (1 paper, 2025). Acute myeloid leukemia (AML) is a group of neoplasms arising from precursor cells committed to the myeloid cell-line differentiation. "By contrast, acute myeloid leukemia (LAML) showed no collagen- or ECM-associated GO categories that significantly correlated with AEBP1, likely reflecting the lack of tumor stroma and the irrelevance of collagen and ECM in hematological malignancies." (PMID 41373631, 2025).
astrocytoma (1 paper, 2025). "Comparison of the grade 3 astrocytoma to the matched normal sample, revealed the top three DEGs encoding ECM glycoproteins (NTN1, AEBP1 and SPARC) and ECM-affiliated factors (C1QA, LGALS9 and C1QL1)." (PMID 41366031, 2025).
classical-like EDS (1 paper, 2023). "Recently, a new subtype of EDS called classical-like EDS type 2 (clEDS2), which is caused by biallelic variants in the adipocyte enhancer binding protein 1 (AEBP1) gene, was identified." (PMID 37214418, 2023).
colorectal adenocarcinoma (1 paper, 2025). The most common type of colorectal carcinoma. "Consistent results were observed in other tumor types, including head and neck squamous cell carcinoma (HNSC), colorectal adenocarcinoma (COADREAD) and pancreatic adenocarcinoma (PAAD), where AEBP1 expression was strongly correlated with expression of both collagen family genes and CAF markers." (PMID 41373631, 2025).
degenerative disc disease (1 paper, 2025). "In this study, we have identified AEBP1 as a tissue marker for monitoring the severity of disc degeneration in humans." (PMID 39930483, 2025). "Based on these findings, AEBP1 may also promote neovascularisation during degenerative disc disease; however, further research is required to elucidate the specific role of AEBP1 in IVD neovascularisation and to assess its potential as a therapeutic target for degenerative disc disease." (PMID 39930483, 2025).
endothelial dysfunction (1 paper, 2024). In vascular diseases, endothelial dysfunction is a systemic pathological state of the endothelium (the inner lining of blood vessels) and can be broadly defined as an imbalance between vasodilating and vasoconstricting substances produced by (or acting on) the endothelium. "Given that endothelial dysfunction is also observed in patients with ME/CFS, such a dysfunction could result from damaged endothelial cells via persistent low-grade inflammation in response to EBNA6_0488 mimicking an AEBP1 peptide." (PMID 38256421, 2024).
Hepatitis (1 paper, 2023). Inflammation of the liver. "When taken up by hepatocytes, the miR-223 that is derived from EV 223 suppresses hepatitis and fibrosis gene expression and decreases miR-372-3p or miR-373-3p, suppressing the adipocyte enhancer-binding protein 1 (AEBP1)." (PMID 37833930, 2023).
hypertrophic cardiomyopathy (1 paper, 2024). A condition in which the myocardium is hypertrophied without an obvious cause. "An in-depth single-nuclei sequencing analysis evaluating lineage-specific changes in pathological cardiac remodeling of hypertrophic cardiomyopathy (HCM) revealed AEBP1 to be a key gene involved in cardiac fibroblast activation and HCM-associated cardiac fibrosis." (PMID 38727290, 2024).
leukemia (1 paper, 2020). A malignant (clonal) hematologic disorder, involving hematopoietic stem cells and characterized by the presence of primitive or atypical myeloid or lymphoid cells in the bone marrow and the blood. "AEBP1 expression was upregulated in multiple leukemia cell lines including Jurkat, Nalm-6, and Raji cells, compared to normal cell line PBMCs." (PMID 32565808, 2020).
myocardial hypertrophy (1 paper, 2021). "It's worth noting that there is no relevant report about the roles of COMP, FMOD, AEBP1 and SULF1 in HOCM or even myocardial hypertrophy, implying the need for further exploration." (PMID 34362365, 2021).
neuropathy (1 paper, 2025). A disorder affecting the nervous system that manifests with pain, tingling, numbness, and/or muscle weakness. "Given that inhibition of the NFκB pathway can alleviate symptoms of neuropathy and promote the function of M2 microglia, we assessed whether the immune response inhibition observed in microglia with downregulated AEBP1 could transition their phenotype to neuroprotective M2 microglia." (PMID 41516171, 2025).
Osteopenia (1 paper, 2021). Osteopenia is a term to define bone density that is not normal but also not as low as osteoporosis. "Biallelic mutations in the AEBP1 gene, encoding AEBP1, cause an EDS phenotype hallmarked by skin hyperextensibility with atrophic scarring, generalized joint hypermobility, foot deformities and early-onset osteopenia, provisionally referred to as classical-like EDS type 2 (clEDS2)." (PMID 34712265, 2021).
parasitic infection (1 paper, 2023). "This, in turn, inhibits Aebp1’s cell-autonomous defense role in the intestinal epithelial cells and allows for a robust parasitic infection." (PMID 37346046, 2023).
prostate carcinoma (1 paper, 2013). A carcinoma that arises from epithelial cells of the prostate gland. "AEBP1 may regulate mitogen-activated protein (MAP)-kinase activity and has been reported to be methylated in rat prostate cancer lines." (PMID 24034811, 2013).
renal carcinoma (1 paper, 2021). A carcinoma arising from the epithelium of the renal parenchyma or the renal pelvis. "For instance, ELK4, CBFB, IFI16, PRRX1, AEBP1, and GATA3 expression was associated with an unfavourable outcome in renal cancer revealing the significance of these TFs (pink and blue colours represent unfavourable and favourable prognosis, respectively)." (PMID 35201514, 2021). "On a similar note, a significant association between the expression of ELK4, CBFB, IFI16, PRRX1, AEBP1, and GATA3 with an unfavourable outcome in renal cancer has been identified in previous reports." (PMID 35201514, 2021).
skin cancer (1 paper, 2020). "Another form of skin cancer where AEBP1 was demonstrated to be an effective therapeutic target is BCC." (PMID 32565808, 2020).
skin ulcerations (1 paper, 2019). "Indeed, AEBP1 knock-out mice show ventral wall defects, develop spontaneous skin ulcerations, and have significantly delayed healing of dermal punch wounds." (PMID 30759870, 2019).
thyroid tumor (1 paper, 2023). A benign or malignant neoplasm affecting the thyroid gland. "Among the identified hub genes, AEBP1, CD34, COL12A1, ITGA2B, THBS2, and TPO exhibit lower expression levels in thyroid tumors." (PMID 37795451, 2023).
tumor (42 papers, 2013 to 2026). "Since constitutive activation of NF-κB is widely implicated in carcinogenesis, AEBP1 overexpression is associated with tumor development and progression." (PMID 32565808, 2020). "As we will discuss later, AEBP1 has been repeatedly associated with tumor progression of different types of cancers via stimulation of collagen formation and ECM remodeling." (PMID 32565808, 2020). "WGCNA analysis of primary BC samples identified AEBP1 as one of the top 50 hub genes associated with tumor node metastasis (TNM) staging in BC patients." (PMID 32565808, 2020). "High expression of AEBP1 was associated with poor overall survival in patients with both early-stage (Tumor, Node, Metastases (TNM) I and II) and late-stage (TNM III and IV) GC." (PMID 30097586, 2018). "Similarly, GO-CC analysis showed that genes related to collagen and the ECM were consistently associated with AEBP1 across tumor types." (PMID 41373631, 2025). "We further investigated whether AEBP1 expression was linked to tumor-associated fibroblasts biomarkers." (PMID 34938806, 2021). "Here, we showed that AEBP1 levels were highly expressed in tumor-associated fibroblasts, which may induce EMT." (PMID 34938806, 2021). "Our results showed that AEBP1 levels were extremely high in tumor-associated fibroblasts, which may induce EMT." (PMID 34938806, 2021). "In addition, our finding suggested that AEBP1 was mainly expressed in tumor-associated fibroblasts and positively associated with fibroblast activation." (PMID 34938806, 2021). "Consistent with this, a recent study reported that CAF-derived AEBP1 protein directly induces T-cell dysfunction by impairing their proliferation and effector functions within the tumor microenvironment." (PMID 41373631, 2025). "This suggests that high expression of ACLP in CAFs enhances tumor stiffness and provides a mechanistic link between stromal AEBP1 expression, collagen remodeling and the biophysical properties of the tumor microenvironment." (PMID 41373631, 2025). "Comparative analysis of AEBP1 (ACLP) expression with CKAP4 expression in human tumor samples will be necessary to elucidate the receptor-ligand axis underlying CAF-mediated tumor remodeling and immune regulation." (PMID 41373631, 2025). "This suggests AEBP1-positive CAFs represent a major source of collagen production within the tumor microenvironment." (PMID 41373631, 2025). "Subsequent GO-BP analysis of 32 TCGA tumor types revealed that, in nearly all cancer types, AEBP1 expression strongly correlated with expression of genes involved in the collagen metabolic process." (PMID 41373631, 2025). "By integrating scRNA-seq datasets, our study further revealed that fibroblasts represent the predominant stromal cell population expressing AEBP1 within tumor tissues." (PMID 41373631, 2025). "It downregulated several potential oncogenes (e.g., AEBP1, MIAT) and genes linked to GBM proliferation and migration (e.g., SOCS2, HCP5) while modulating Wnt signaling and up-regulating tumor suppressor genes (e.g., SPRY4, BEX2)." (PMID 39874307, 2025). "AEBP1 levels were also elevated in tumour endothelial cells thereby promoting angiogenesis within the tumour microenvironment." (PMID 39930483, 2025). "AEBP1 is predominantly expressed in CAFs within the tumor microenvironment and is positively correlated with PD-L1 expression, T-cell dysfunction, and poor patient survival." (PMID 41149482, 2025). "Further elucidation of the mechanism by which AEBP1 inhibits skeletal muscle cell differentiation is expected to lead to the development of new cancer therapies that disrupt the tumor microenvironment." (PMID 39521917, 2024). "We previously found that upregulation of AEBP1 in vascular endothelial cells promotes tumor angiogenesis in colorectal cancer." (PMID 39521917, 2024). "Research suggests that the upregulation of AEBP1 can contribute to tumour angiogenesis in primary CRC." (PMID 36902343, 2023).